IGF2BP2 (insulin like growth factor 2 mRNA binding protein 2)
Diseases named in the same sentence as IGF2BP2 in open-access papers (continued):
Sharing a sentence is not in itself a finding about the gene and the disease.
bladder cancer (17 papers, 2020 to 2026). "Additionally, the differential expression analysis of the GSE146726 dataset showed that IGF2BP2 loss led to the differential expression of 1040 or 920 genes in UMUC3 or J82 bladder cancer cells, respectively." (PMID 34709120, 2022). "The m6A reader IGF2BP2 facilitates M2 macrophage polarisation and enhances the malignant behaviour of bladder cancer by stabilising NRP1 mRNA expression." (PMID 41527491, 2026). "Exosome-transmitted LUCAT1 promotes the stemness phenotype and chemoresistance of BC cells via upregulating HMGA1 expression via binding to IGF2BP2, thus contributing to its oncogenic activity in bladder cancer pathogenesis." (PMID 40025525, 2025). "Subsequently, through univariate Cox regression analysis, we identified ALKBH5, FTO, IGF2BP2, and IGF2BP3 as potential risk factors for bladder cancer." (PMID 40083693, 2025). "In bladder cancer, circZNF609 enhances fatty acid uptake via the IGF2BP2/CD36 pathway, leading to metabolic reprogramming that reduces tumor sensitivity to immunotherapy." (PMID 41438756, 2025). "(A) Relative enrichment of circHIPK3 levels or ACTB mRNA between IP and input for the three RNA-binding proteins (RBPs) GRWD1, IGF2BP1, and IGF2BP2 in the bladder cancer cell line FL3." (PMID 39041323, 2024). "This study reveals that in the bladder cancer microenvironment, epithelial cells with elevated IGF2BP2 expression can recruit monocytes/macrophages." (PMID 39711402, 2024). "Absolute quantifications suggest low levels of circHIPK3 compared to IGF2BP2, where high circHIPK3 levels correlate with increased survival of bladder cancer (BC) patients." (PMID 39041323, 2024). "By mining eCLIP datasets and combined with RNA immunoprecipitation assays, we demonstrate that the 11-mer motif constitutes a strong binding site for IGF2BP2 in bladder cancer cell lines." (PMID 39041323, 2024). "WTAP mediates PIGT m6A modification to increase the stability of PIGT via the IGF2BP2, which enhances cell proliferation, glycolysis, and metastasis in bladder cancer by modulating GLUT1 glycosylation and membrane trafficking." (PMID 38169393, 2024). "This occurs through the upregulation of IGF2BP2, which facilitates immune escape of bladder cancer cells." (PMID 39628486, 2024). "Compared to urothelial cell line (SV-HUC-1 cells), the expression levels of IGF2BP2 were found to be relatively high in the bladder cancer cell lines UMUC3 and T24 cells." (PMID 36569935, 2022). "Consistent with our observations in HepG2, circCDYL is much higher expressed than the mRNAs of its interacting RBPs, IGF2BP1 (> 180×) and IGF2BP2 (> 5×), in both bladder cancer cell lines, supporting circCDYL’s potential to act as a sponge." (PMID 33287884, 2020). "Additionally, developing safe and effective interventions targeting the LUCAT1/IGF2BP2/HMGA1 signaling axis to effectively inhibit the stemness transformation of bladder cancer cells and suppress chemotherapy resistance warrants further investigation." (PMID 40025525, 2025). "Our investigation has revealed that cancer stem cell-derived exosomal LUCAT1 enhances the stemness phenotype and chemoresistance of bladder cancer cells by upregulating HMGA1 expression through its interaction with IGF2BP2, thereby contributing to the oncogenicity of bladder cancer." (PMID 40025525, 2025). "Collectively, these results establish IGF2BP2 as a critical m6A regulator influencing BC subgroups, the tumor microenvironment, and clinical outcomes, highlighting its potential as a biomarker for therapeutic stratification in bladder cancer." (PMID 39711402, 2024). "Moreover, immunofluorescence performed on bladder cancer tissue samples revealed that samples with high IGF2BP2 expression exhibited relatively high levels of CD14 and CD68, consistent with the TCGA‐BLCA and spatial transcriptomics findings." (PMID 39711402, 2024).
bladder cancer (continued). "Given its role in shaping the TME and influencing immune cell infiltration, IGF2BP2 may serve as a potential therapeutic target for enhancing the efficacy of immunotherapy in bladder cancer." (PMID 39711402, 2024). "However, the role and mechanism of IGF2BP2 in bladder cancer (BCa) still deserves to be further revealed." (PMID 39014364, 2024). "While research has highlighted the involvement of IGF2BP2 in various cancers, its definitive role in bladder cancer and association with the immune microenvironment are not fully elucidated." (PMID 39711402, 2024). "Similarly, circZNF609 stabilizes the IGF2BP2/CD36 complex in bladder cancer to promote fatty acid uptake, thereby activating PPAR signaling and supporting lipid-dependent tumor growth while impairing T-cell metabolic fitness and reducing immunotherapy responsiveness." (PMID 41438756, 2025). "To validate the role of IGF2BP2 in macrophage recruitment, we conducted a co‐culture assay using THP‐1‐derived M0 macrophages and UM‐UC‐3 bladder cancer cells." (PMID 39711402, 2024). "The results indicate a novel role of WTAP in bladder cancer, demonstrating that WTAP increases the m6A modification of PIGT through IGF2BP2 to contribute to bladder cancer progression." (PMID 38169393, 2024). "In bladder cancer cell lines, we show that circCDYL interacts with IGF2BP1 and IGF2BP2 and that depletion of circCDYL or these RBPs disturb several hallmarks of cancer." (PMID 33287884, 2020). "In bladder cancer (BLCA), NSUN2, IGF2BP2, YTHDC1, ALKBH5, TRDMT1, and ZC3H13 were identified, with NSUN2—a 5-methylcytosine (m5C) writer—previously shown to promote tumorigenesis and cancer stemness by stabilizing CCND1 mRNA and driving epithelial–mesenchymal transition." (PMID 40565233, 2025). "This study demonstrated a novel function of PIGT, showing that PIGT enhances cell growth, glycolysis, and metastasis in bladder cancer by modulating GLUT1 glycosylation and membrane trafficking and that WTAP increases m6A modification of PIGT through m6A reader, IGF2BP2." (PMID 38169393, 2024).
esophageal squamous cell carcinoma (15 papers, 2020 to 2025). Esophageal squamous cell carcinoma (ESCC) is a type of esophageal carcinoma (EC) that can affect any part of the esophagus, but is usually located in the upper or middle third. "The lncRNA TMEM44-AS1, for instance, can inhibit ferroptosis and stabilize GPX4 mRNA, thus promoting the malignant growth of esophageal squamous cell carcinoma (ESCC) by binding to the RNA-binding protein IGF2BP2." (PMID 40271153, 2025). "Long non‐coding RNA HOXC‐AS1 exerts its oncogenic effects in esophageal squamous cell carcinoma by interaction with IGF2BP2 to stabilize SIRT1 mRNA expression." (PMID 36510377, 2023). "Further rescue experiments revealed that circRUNX1 was involved in the regulation of IGF2BP2 in terms of proliferation and metastasis of esophageal squamous cell carcinoma." (PMID 36522683, 2022). "Moreover, linc01305 increases the stability of HTR3A mRNA by interacting with IGF2BP2, thereby promoting the metastasis and proliferation of esophageal squamous cell carcinoma." (PMID 35299748, 2022). "In addition, FOXP4-AS1 positively regulated FOXP4 by interacting with insulin-like growth factor 2 mRNA-binding protein 2 (IGF2BP2) to stabilize FOXP4 mRNA in esophageal squamous cell carcinoma." (PMID 33604387, 2021). "This study demonstrates that the RNA‐binding protein IGF2BP2 binds to and stabilizes LINC02820, leading to elevated LINC02820 expression in esophageal squamous cell carcinoma (ESCC)." (PMID 40416600, 2025). "LINC01305 has been shown to regulate the target gene HTR3A mRNA through interaction with IGF2BP2 and IGF2BP3, thereby participating in the metastasis and proliferation of esophageal squamous cell carcinoma." (PMID 36204323, 2022). "In esophageal squamous cell carcinoma, SNHG12 regulates BMI1 expression via sponging miR‐6835‐3p and enhances CTNNB1 stability via recruiting IGF2BP2." (PMID 32239639, 2020). "In esophageal squamous cell carcinoma (ESCC), LncRNA CCAT2 increases IGF2BP2 expression, and then IGF2BP2 improves mRNA stability of thymidine kinase 1 (TK1) in m6A modification manner, which promotes tumor progression." (PMID 35541906, 2022).
leukemia (15 papers, 2018 to 2026). A malignant (clonal) hematologic disorder, involving hematopoietic stem cells and characterized by the presence of primitive or atypical myeloid or lymphoid cells in the bone marrow and the blood. "The flow cytometry staining confirmed that the IGF2BP2 deficiency significantly decreased the human CD45+ leukemia burden in the bone marrow, spleen and peripheral blood." (PMID 35915142, 2022). "Consistently, the mice bearing IGF2BP2-deficient cells manifested ameliorated splenomegaly, more reddish bones, and suppressed leukemia cell dissemination in the bone marrow and spleen." (PMID 35915142, 2022). "IGF2BP2 is notably overexpressed in leukemia stem cells (LSCs), correlating with poor prognosis in patients with AML." (PMID 40141058, 2025). "The inhibition of IGF2BP2 by a recently discovered small molecule compound (CWI1-2) shows promising anti-leukemia effects both in vitro and in vivo." (PMID 38727270, 2024). "JX5 shows cytotoxicity against Jurkat cells with IGF2BP2 overexpressed but only mild inhibition in normal Jurkat cells, suggesting therapeutic potential for IGF2BP2‐positive leukaemia." (PMID 38545841, 2024). "CWI1-2 and JX5 have been identified as IGF2BP2 inhibitors, which selectively disrupt the binding of IGF2BP2 to its m6A modified target RNAs and exhibit good anti-leukemia activity." (PMID 37714846, 2023). "For example, BTYNB has already been verified to target both IGF2BP1 and IGF2BP2, inhibiting leukemia initiation and development." (PMID 37280679, 2023). "Moreover, CWI1-2 has also been shown to effectively inhibit IGF2BP2 protein expression and demonstrates potent anti-leukemia efficacy." (PMID 40362183, 2025). "It has been shown that the m6A-binding protein IGF2BP2 promotes AML development and leukemia stem cell (LSC) self-renewal in an m6A-dependent manner by regulating key targets in the glutamine metabolism pathway (such as MYC, GPT2, and SLC1A5)." (PMID 38727270, 2024). "Among them, IGF2BP-1 has been reported to inhibit IGF-II mRNA translation during development while on the other hand IGF2BP-2 and -3 were previously shown to promote IGF-II mRNA translation in rhabdomyosarcoma and leukemia respectively." (PMID 30733684, 2018). "Additionally, in vivo bone marrow transplantation assays in mice demonstrate that IGF2BP2 knockout significantly delays AML progression, reduces leukemia cell engraftment, and prolongs survival." (PMID 40141058, 2025). "In AML, IGF2BP2 stabilizes protein arginine methyltransferase 6 (PRMT6) and subsequently downregulates the expression of the lipid transporter major facilitator superfamily domain containing 2A (MFSD2A), thereby maintaining the function of leukemia stem cells." (PMID 38721006, 2024). "Research has shown that by inhibiting IGF2BP2, CWI1-2 can regulate the expression of key targets (such as MYC, GPT2, and SLC1A5) in the glutamine metabolism pathway in an m6A-dependent manner, thereby inhibiting the development of AML and the self-renewal of leukemia stem cells." (PMID 38790013, 2024). "Interestingly, induced expression of structurally and functionally related paralogs Igf2bp1 and Igf2bp2 was noted with enforced expression of non-MLL-Af4 oncogenic drivers, again in concordance with observations in human leukemia." (PMID 34321607, 2022).
liver cancer (15 papers, 2020 to 2025). An epithelial or non-epithelial malignant neoplasm that arises from the liver. "For example, IGF2BP2 promotes tumor development in liver cancer by binding to mRNAs with stem cell characteristics, such as OCT4." (PMID 40088376, 2025). "For example, IGF2BP2 maintains FEN1 expression through an m6A-dependent mechanism to promote liver cancer growth." (PMID 37744330, 2023). "For instance, IGF2BP2 presents a high expression in liver cancer tissues and facilitates liver cancer development via the m6a-Flap endonuclease 1 (FEN1)-dependent mechanism." (PMID 35014946, 2022). "IGF2BP2 promotes the liver cancer growth via FEN1; however, its role in iron metabolism remains unclear." (PMID 37088822, 2023). "It was found that rtcisE2F acts as a scaffold to promote the interaction between IGF2BP2 and E2F6/E2F3 mRNAs, thereby maintaining their stability and driving the self-renewal of liver cancer cells." (PMID 41155268, 2025). "IGF2BP2 interacts with and stabilizes FEN1 mRNA from decay in liver cancer." (PMID 37142269, 2023). "Overall, our study revealed that METTL3 and IGF2BP2, acting as an oncogene, maintained FEN1 expression through an m6A-IGF2BP2-dependent mechanism in HCC cells, and indicated a potential biomarker panel for prognostic prediction in liver cancer." (PMID 33224879, 2020).
non-small cell lung carcinoma (15 papers, 2020 to 2026). A group of at least three distinct histological types of lung cancer, including non-small cell squamous cell carcinoma, adenocarcinoma, and large cell carcinoma. "A study has demonstrated that alterations in IGF2BP2 expression are linked to dasatinib resistance in non-small cell lung cancer cells." (PMID 40088376, 2025). "Also, in non-small-cell lung cancer, IGF2BP2 enhances the proliferation of tumor cells by binding to the oncogenic MALAT1 lncRNA and increasing its stability." (PMID 35664076, 2022). "For example, circNDUFB2 could facilitate the ubiquitination and degradation of IGF2BP2 to modulate cellular immune responses in non-small cell lung cancer." (PMID 36072601, 2022).
prostate carcinoma (14 papers, 2020 to 2025). A carcinoma that arises from epithelial cells of the prostate gland. "Insulin-like growth factor 2 mRNA-binding protein 2 (IGF2BP2), which binds with high affinity to numerous RNA transcripts, is known to promote tumorigenesis and metastasis, including in prostate cancer (PCa)." (PMID 40084251, 2025). "Our analysis revealed that IGF2BP2 is significantly upregulated in CRPC patient samples compared to primary prostate cancer samples (p < 0.01, logFC = 1.88)." (PMID 39948708, 2025). "At the same time, aberrant activation of the PCAT6/IGF2BP2/IGF1R axis will promote both the growth of prostate cancer and its metastasis to bone." (PMID 39771106, 2024). "A notable example is the lncRNA DANCR, which is regulated by IGF2BP2 in an m6A methylation-dependent manner, promoting stem cell-like properties, cancer cell proliferation, and contributing to the progression of prostate cancer (PC)." (PMID 39596216, 2024). "Among these 3 genes, only IGF2BP2 expression was down-regulated in prostate cancer, and the ROC curve showed that the AUC of IGF2BP2 was higher than that of the other 2 genes for distinguishing between normal and cancer tissues." (PMID 38384328, 2024). "Western blot analysis used to determine protein expression demonstrated that si-IGF2BP2/3 inhibited the TGF-β-induced production of DDIT4 in prostate cancer cells." (PMID 38384328, 2024). "PCAT6 promotes prostate cancer bone metastasis by stabilizing IGF1R mRNA through interacting with IGF2BP2." (PMID 34185427, 2021). "IGF2BP2 mRNA and protein are frequently overexpressed across a wide variety of cancer types, as exemplified by proposals for IMP2 expression to be used as a predictive biomarker in prostate cancer as part of a panel of tumor-associated antigens." (PMID 40141058, 2025). "It has been speculated that the role of IGF2BP2/3 in regulating the stability of target genes in prostate cancer may be affected by the expression level of AR, but the precise mechanism remains unclear." (PMID 38384328, 2024). "Moreover, the measurement of the rate of RNA decay in prostate cancer cells with IGF2BP2/3 silencing and corresponding controls showed that the DDIT4 mRNA level was decreased and the mRNA half-life was significantly shortened after IGF2BP2/3 silencing in LNCaP cells." (PMID 38384328, 2024). "To determine the clinical relevance of IGF2BP2 in CRPC, we analyzed the mRNA expression data for prostate cancer patients available in the Genomic Data Commons (GDC) Data Portal and cBioPortal." (PMID 39948708, 2025).
lung adenocarcinoma (11 papers, 2018 to 2025). A carcinoma that arises from the lung and is characterized by the presence of malignant glandular epithelial cells. "Although past reports have shown that in lung adenocarcinoma, IGF2BP2 can affect cell proliferation, migration, and invasion, we found that knocking down TMEM99 does not affect IGF2BP2 expression and vice versa." (PMID 40704413, 2025). "The m6A methylation reader IGF2BP2 activated endothelial cells to promote lung adenocarcinoma angiogenesis and metastasis." (PMID 39160604, 2024). "At the same time, IGF2BP2 protein expression was also upregulated in lung adenocarcinoma cell lines relative to normal lung cells." (PMID 35011587, 2021). "The RT-PCR results confirmed that both WT1-AS and IGF2BP2 were significantly upregulated in lung adenocarcinoma cell lines relative to the normal bronchial epithelial cell line BEAS-2B, and the highest expression was found in PC-9 cells." (PMID 35011587, 2021). "Finally, the expression of WT1-AS, IGF2BP2, and miR-200a-3p in lung adenocarcinoma cell lines was verified by RT-PCR." (PMID 35011587, 2021). "Previous study had suggested that IGF2BP2 elevated FLT4 stability via m6A modification, thus accelerating angiogenesis and metastasis of lung adenocarcinoma cells." (PMID 39014364, 2024). "For example, METTL3 increased m6A modification of PCAT6, resulting in PCAT6 upregulation in an IGF2BP2-dependent manner; LCAT3 stability was significantly increased in a METTL3-dependent manner in lung adenocarcinomas, thereby activating MYC transcription via FUBP1." (PMID 35037556, 2022). "The results revealed that the levels of IGF2BP1, particularly IGF2BP2 and IGF2BP3, were remarkably upregulated in many cancer types such as bladder urothelial carcinoma (BLCA), liver hepatocellular carcinoma (LIHC), lung adenocarcinoma (LUAD), and lung squamous cell carcinoma (LUSC)." (PMID 35003212, 2021).
oral squamous cell carcinoma (11 papers, 2022 to 2025). "METTL14 suppresses the development of oral squamous cell carcinoma by activating autophagy via m6A/IGF2BP2-dependent modification on FIP200 stability." (PMID 39897540, 2025). "Another study of oral squamous cell carcinoma suggested that IGF2BP2 regulates immune inflammation cytokines and correlates with immune infiltrates." (PMID 38960931, 2024). "Yet, the functional involvement of IGF2BP2 in the progression of oral squamous cell carcinoma (OSCC) remains poorly understood." (PMID 38250159, 2024). "As for the role that IGF2BP2 plays in immune response, study showed that IGF2BP2 could affect the immune-related biological pathways in oral squamous cell carcinoma, thus leading to the worse prognosis for cancer." (PMID 38637813, 2024). "Notably, IGF2BP2 has been shown to stabilize HK2 mRNA, thereby promoting the Warburg effect and driving the progression of oral squamous cell carcinoma." (PMID 41394397, 2025).
pancreatic ductal adenocarcinoma (11 papers, 2021 to 2026). An infiltrating adenocarcinoma that arises from the epithelial cells of the pancreas. "Another study suggested that upregulated IGF2BP2 may cause poor prognosis in pancreatic ductal adenocarcinoma." (PMID 33637103, 2021). "IGF2BP2 is frequently overexpressed in pancreatic ductal adenocarcinoma (PDAC) and gallbladder carcinoma (GBC) and is significantly associated with poor prognosis." (PMID 33952279, 2021). "IGF2BP2, as an N6- methyladenosine (m6A) reader, has been reported to be able to directly bind to and stabilize GLUT1 mRNA in pancreatic ductal adenocarcinoma and CRC." (PMID 37957183, 2023). "Given that IGF2BP2 could directly bind to and stabilize GLUT1 mRNA in pancreatic ductal adenocarcinoma and CRC, we inferred whether HES1 modulated GLUT1 expression via IGF2BP2 in an m6A modification-dependent manner." (PMID 37957183, 2023).